IL10 (interleukin 10)
Diseases named in the same sentence as IL10 in open-access papers (continued):
Sharing a sentence is not in itself a finding about the gene and the disease.
COVID-19 (continued). "In another study, transplantation of MSCs in COVID-19 patients was associated with a significant increase in anti-inflammatory cytokines (IL-10, IL-13) and also a significant decrease in pro-inflammatory cytokines, i.e., IFN-γ, IL-6." (PMID 37365605, 2023). "In previous studies, increased TNF-α, IL-1Ra, IL-6, IL-8, IL-15 and IL-10 serum levels were associated with higher mortality in COVID-19." (PMID 37969879, 2023). "Increased fecal levels of IL-8 and lower fecal levels of IL-10 in COVID-19 hospitalized patients.Fecal IL-23 is higher in more severe COVID-19.Intestinal virus-specific IgA responses are associated with more severe disease." (PMID 37006316, 2023). "The current study also assessed the relationship of polymorphisms of the cytokine genes IL2, IL6, and IL10 with the severity of COVID-19 in Kazakh population." (PMID 37390087, 2023). "The predicted IL-10 levels in this study showed much more significant associations with COVID-19 mortality (p-value = 3.630e-10) than the original levels (p-value = 8.787e-6)." (PMID 37735372, 2023). "Our results also confirm the association of the IL10 rs1800872 polymorphism and D-dimer with the severity of COVID-19 in the Kazakh population." (PMID 37390087, 2023). "Acute COVID-19 was associated with marked elevations in nearly all pro-inflammatory markers, whilst eleven markers (namely IL-1β, IL-2, IL-6, IL-10, IL-18, IL-23, IL-33, TNF-α, IP-10, G-CSF and YKL-40) were associated with disease severity." (PMID 37063871, 2023). "Another study also showed that COVID-19 severity was linked with higher levels of proinflammatory cytokines in the first waves of the pandemic, with IL-8, IL-6, and IL-10 having the highest AUC values." (PMID 36766961, 2023). "In patients with COVID-19, the allele T (0.37) for the IL10 rs1800872 as MAF was directly correlated with death." (PMID 36882862, 2023). "The obtained results indicated that the CC IL10 rs1800871, TT, and GG genotypes with rs1800872 and rs1800896 polymorphisms were significantly associated with mortality from COVID-19 compared to other genotypes." (PMID 37390087, 2023). "Shed P2X7R also significantly correlated with IL-10 (r = 0.336; p = 0.008), a cytokine very likely implicated in COVID-19 pathogenesis and often elevated in COVID-19 patients." (PMID 37215142, 2023). "Further molecular docking revealed that quercetin has a higher affinity for IL6 and IL10 in the TNF signaling pathway associated with COVID-19." (PMID 38050310, 2023). "Vector analysis conducted in the 1st trimester indicated that CXCL8, CCL3, CCL5, IL-1β, TNF-α, IL-12, IL-15, IL-1Ra, IL-10, and G-CSF were associated with convalescent COVID-19 in pregnant women." (PMID 37122732, 2023). "In our study, patients with eosinopenia had higher levels of IL-10, which has been identified as a predictor for rapid diagnosis of COVID-19 patients at higher risk of disease deterioration." (PMID 38162638, 2023). "D-dimer is also associated with IL10 rs1800872 gene polymorphism in the Kazakh population with severe COVID-19." (PMID 37390087, 2023). "Mainly, PAL was associated with changes in IL-10, triglyceride, and leptin levels in the plasma of post-COVID-19 patients." (PMID 37753077, 2023). "Actually, the immunoregulatory cytokine IL-10, which is commonly linked to immunological tolerance, but also a well-accepted disease marker in COVID-19,38,39 was particularly low in long-term carriers." (PMID 37529320, 2023). "In this regard, the present study provided an evidence that IL-10 (rs1800872) gene polymorphism is strongly associated with COVID-19 severity and CC genotype confer a protective role in preventing severe disease progression." (PMID 37521849, 2022). "Levels of four cytokines (IL-6, IL-10, IL-18, IL-27) were consistently elevated in patients with COVID-19 independently of the variant." (PMID 36430621, 2022).
COVID-19 (continued). "Analyses of cytokines have shown that serum levels of IL-1β, IL-6, IL-10, IL-23, IL-33 and Gal-1 are in significant positive association with increased COVID-19 severity." (PMID 35075140, 2022). "Multivariate analysis shows that IFN gamma and IL-10 are the most powerful risk factors for mortality in the COVID-19 patient group." (PMID 36286038, 2022). "We found that DNA methylation changes in severe COVID-19 patients share some features with sepsis, especially those associated with the expression of tolerogenic cytokines like IL-10." (PMID 36443794, 2022). "Our results show that IFN-gamma and IL-10 are the most powerful risk factors for mortality in the COVID-19 patient groups in our multivariate analysis." (PMID 36286038, 2022). "IL-6, CRP, and IL-10 and have also been associated with disease severity amongst COVID-19 patients, correlating with severe clinical outcomes and fatality." (PMID 36268187, 2022). "In conclusion, both asymptomatic SARS-CoV-2 infected blood donors and patients with severe COVID-19 share an inflammatory profile; however, high levels of IL-6, IL-10, and CCL5 were significantly associated with severe infection outcomes." (PMID 36287506, 2022). "Prior studies have also identified IP-10 and IL-10 as biomarkers with more specificity for viral infection, including COVID-19, relative to other causes of respiratory failure." (PMID 36104754, 2022). "In this study, we found ddcfDNA was significantly elevated in SOTRs with COVID-19 and strikingly correlated with cytokines/chemokines (IL-10, IL-8, IL-2Ra, IL-18, GM-CSF and IL-12p70) associated with CRS." (PMID 35075453, 2022). "We also measured secreted IL-6, associated with the acute inflammatory response in COVID-19 and influenza, as well as the increased production of anti-inflammatory IL-10, which maintains immune homeostasis." (PMID 35962146, 2022). "This study provides relevant information regarding the prevalence of COVID-19 and long COVID in HD patients and suggested phosphate and interleukin (IL-10) as possible targets associated with post-COVID conditions." (PMID 36248863, 2022). "Several studies have consistently found an association between high plasma concentrations of IL-6 and IL-10 and increased COVID-19 severity." (PMID 36287506, 2022). "A massive pro-inflammatory profile mediated by IL-1β, IL-6, TNF and IFN-γ together with lower levels of IL-10 was a systemic hallmark of critically ill COVID-19 patients." (PMID 35720401, 2022). "A cytokine storm characterized by elevation in the serum concentrations of several pro-inflammatory cytokines is a hallmark of COVID-19, with IL-6 and IL-10 being significantly elevated in those with critical disease." (PMID 35335635, 2022). "A proposed pathogenetic mechanism involving the role of interleukin (IL)-10 and IL-6 can be considered when analyzing the association between aspergillosis and COVID-19." (PMID 35050031, 2022). "In case of IL-10 (rs1800872) gene polymorphism, a significant protective role of CC genotype was observed in preventing COVID-19 severity among infected patients (p = 0.010)." (PMID 37521849, 2022). "High levels of IL-10 levels in early illness in patients with COVID-19 were shown to associate with poorer disease outcomes and was shown to be a predictor of severe disease along with IL-6." (PMID 35786403, 2022). "It is currently acknowledged that severe forms of COVID-19 are associated with the release of cytokines, such as IL-2, IL-6, IL-7, IL-10, tumor necrosis factor (TNF), and granulocyte colony-stimulating factor (GCSF)." (PMID 35743583, 2022). "COVID-19 active infection is associated with increased IL-10 and WBC with a concomitant decrease in IFN-γ and haemoglobin concentration." (PMID 36094915, 2022). "IL-10, the other COVID-19 named before as a COVID-19 prognostic cytokine, has been associated with an impaired function of mucosal-associated innate T cells (MAIT), which are innate-like T cells with a semi-invariant T cell receptor (TCR)." (PMID 36142625, 2022).
COVID-19 (continued). "More detailed studies with a larger sample size on the genetic variations are required to establish the role of studied IL-10 gene polymorphisms with COVID-19 severity." (PMID 37521849, 2022). "This study was thus carried out to determine the association of rs1800896 and rs1800872 genetic polymorphism in IL-10 gene in determining COVID-19 severity." (PMID 37521849, 2022). "This is consistent with the clinical observations which showed elevated circulating levels of IL-10 in patients with CRS associated with COVID-19, TGN1412, and CAT-T cell therapy." (PMID 35330839, 2022). "In this regard, the present study provided an evidence that IL-10 (rs1800872) gene polymorphism is strongly associated with COVID-19 severity where, CC genotype confer a protective role in preventing severe disease progression." (PMID 37521849, 2022). "In conclusion, we found that serum levels of IL-6, IL-8, and IL-10 were associated with the disease severity of COVID-19 patients, and serum levels of IL-1β, IL-6, and IL-8 were associated with the prognosis of COVID-19 patients." (PMID 35540724, 2022). "Overall, high levels of TNF-α, IL-6, IL-8, and IL-10 have been associated with disease severity and poor survival from COVID-19." (PMID 34987205, 2022). "COVID-19 active infection is associated with increased IL-10 and WBC with a conconmittant decrease in IFN-γ and haemoglobin concentation." (PMID 36094915, 2022). "Several cytokines have been proposed to be potential biomarkers of COVID-19 severity; interferon gamma–induced protein 10 (IP-10), interleukin (IL)-6, and IL-10 have been associated consistently with greater severity of this disease." (PMID 34386533, 2021). "Some studies reported an association between early high IL-10 levels and poor clinical outcomes in severe COVID-19 cases." (PMID 34831410, 2021). "COVID-19 and cancers were associated with lymphopenia and high levels of monocytes, neutrophils, IL-6, and IL-10." (PMID 34712741, 2021). "But few epidemiological studies provided direct support for the associations of serum ferritin and IL-10 with COVID-19 fatal risk." (PMID 33410720, 2021). "Baricitinib inhibits the intracellular signaling pathway of cytokines implicated in severe COVID-19, including IL-2, IL-6, IL-10, IFN-γ, and granulocyte-macrophage colony-stimulating factor (GM-CSF)." (PMID 34063964, 2021). "A practical approach to model application for the estimation of the risk of progression to severe COVID-19 would be to measure IL-10 and IL-12 (p70) levels on admission in hypertensive patients with two or three of the relevant clinical comorbidities." (PMID 34386533, 2021). "In conclusion, both COVID-19 and cancers were associated with lymphopenia and high levels of monocytes, neutrophils, IL-6, and IL-10." (PMID 34712741, 2021). "Several inflammatory CCs and notably MCP1, IP10, IL6, IL1Ra, IL10 and TNFa had more associations (COVID-19) with the BIMs suggesting that these CCs are the inflammatory markers driving brain injury." (PMID 34838058, 2021). "Correlation analysis identified that many metabolites were associated with proinflammatory IL-6 and anti-inflammatory IL-10 cytokine levels, suggesting a potential cytokine-mediated metabolic dysfunction from COVID-19 pathogenesis." (PMID 34307393, 2021). "Consistent with published studies, we observed high concentrations of inflammation-associated cytokines, including IL-6, TNF-α, IP-10, IL-10, IL-1α and IL-1β, in serum and nasal lining fluid from PCR-confirmed COVID-19 patients." (PMID 34117221, 2021). "In this study, we identified six candidate features, including disease severity, age, and serum levels of hs-CRP, LDH, ferritin, and IL-10 measured at hospital admission, as critical death risk biomarkers for COVID-19 patients." (PMID 33410720, 2021).
COVID-19 (continued). "Recent clinical reports have shown that inflammation was induced in COVID-19 cases, and this induction was associated with an increased level of cytokines, including interleukins (IL-1β, IL-6, IL-10) and tumor necrosis factor-α (TNF-α)." (PMID 34901061, 2021). "It is currently admitted that severe forms of COVID-19 are associated with a release of cytokines and chemokines such as IL-2, IL-6, IL-7, IL-10, tumor necrosis factor (TNF), and granulocyte colony-stimulating factor (GCSF)." (PMID 34552938, 2021). "Accordingly, studies have linked higher levels of IL-10 in patients with COVID-19 to increased production of other systemic inflammatory cytokines, which can contribute to the severity of the disease." (PMID 34336904, 2021). "Elevated levels of TNFα and other pro-inflammatory cytokines and chemokines, such as IL-6, IL-10 are risk factors for the development of severe COVID-19, and their levels are much higher in critical patients than in those with milder disease." (PMID 33465050, 2021). "In our analysis we observed that several biomarkers, including GM-CSF, MCP-1, MIP1α, TNFα, IL-1RA, IL-6, IL-8, IL-15 and IL-10 were associated with fatal outcomes in COVID-19." (PMID 34539631, 2021). "Further, inflammatory dysregulated IL-2, IL-6, IL-10 and IL-15 are associated with COVID-19-related mortality." (PMID 34117221, 2021). "Several of these cytokines have been implicated as mediators of COVID-19; for instance, IL-6, IL-4, IL-10 and IFNγ." (PMID 34214142, 2021). "The ACE polymorphism has been reported to be associated with cytokines such as IL-6, IL-8, and IL-10, which are biomarkers of severe COVID-19 patients." (PMID 35095487, 2021). "The association of the IL-10 level with COVID-19 progression to severity has been reported in a considerable number of publications." (PMID 34386533, 2021). "Nevertheless, they suggest that IL-10 is the only of these cytokines for which an increase is associated with pediatric COVID-19 whereas increases of all six are seen in adult patients." (PMID 33746948, 2021). "It has been demonstrated that the extensive release of inflammatory mediators such as TNF-α, IL-6, and IL-10 is associated with increased mortality risk in COVID-19 patients." (PMID 33997001, 2021). "As a whole, the levels of IL-6 and IL-10 were significantly higher in severe COVID-19 from our results, suggesting a more serious cytokine storm underlying the pathogenesis of COVID-19." (PMID 33552062, 2020). "In accordance with studies from S-XW and JL, we also found that the levels of IL-6 and IL-10 were associated with the severity of COVID-19." (PMID 33349241, 2020). "The cytokine storm has been widely reported to occur in severe COVID-19 and bacterial sepsis and many studies have shown that elevated levels of some cytokines, such as IL-6 and IL-10, are associated with mortality." (PMID 33329592, 2020). "Macrophage produced TNF-α causes apoptosis of effector T cells, while IL-10 produced by lung macrophages in severe COVID-19 prevents T cell responses." (PMID 34192268, 2020). "COVID-19 patients also show heightened IL-4 and IL-10 levels, cytokines associated with inhibitory inflammatory responses." (PMID 32803199, 2020). "COVID-19 is associated with both immunodeficiency and hyperinflammation, and T cell numbers are negatively correlated with serum IL-6, IL-10 and TNF-α." (PMID 33365277, 2020). "Abnormal concentrations of several associated cytokines like TNF, IL-10, and IL-6 were found in COVID-19 patients." (PMID 33224256, 2020). "Symptoms of severe COVID-19 have been associated with a cytokine storm with high levels of IL-17, IL-10, IL-1β, IL-2, IL-7, IL-8, IL-9, among many other pro-inflammatory cytokines." (PMID 33071815, 2020).
COVID-19 (continued). "In our study, we described the demographical and clinical characteristics of patients with COVID-19 stratified by severity and assessed associations to infer the potential use of inflammatory cytokines (IL-2, IL-4, IL-6, IL-8, IL-10, TNF-α, GM-CSF, and IFN-γ) as biomarkers of COVID-19 pneumonia." (PMID 40508859, 2025). "Analysis of the ROC curve results revealed common markers between patients with severe COVID-19 and both HV and convalescent groups, including IL-1Ra, IL-10, and sICAM-1, as diagnostic tools to distinguish between health conditions with high sensitivity and specificity." (PMID 41583455, 2025). "In addition, COVID-19 patients with GG and AG genotypes and the G allele of the IL-10 gene’s–1,082 A/G polymorphism experience less severe ARDS." (PMID 40761632, 2025). "We therefore considered whether IL-10 mediated positive associations between pro-inflammatory cytokines and risk of hospitalization or death from COVID-19 in the UKB." (PMID 41280118, 2025). "That patients with MASLD might have different immune responses was shown in COVID-19, where several cytokines and chemokines were linked with uncontrolled inflammation and development of severe/critical disease (such as IL-6, IL-8, IL-10, TGF-β1 and CXCL10)." (PMID 40076848, 2025). "Regarding IL-10, the odds of a low concentration (less than the second quintile) was significantly associated with COVID-19 severity (OR > 1 with p = 0.019); similar results were obtained by bivariate analyses and when adjusting for time elapsed from negative test." (PMID 39194742, 2024). "To explore the mechanisms of decreased expression of PD-1 in CD4+ and CD8+ T cells from convalescent COVID-19 patients, we measured plasma cytokines associated with PD-1 expression, including IL-2, IL-6, IL-7, IL-10, IL-12p70, IL-33, IFN-γ and CCL19/MIP-3, by Luminex." (PMID 38424104, 2024). "A dysregulation in cytokine content has been linked to T cell exhaustion in patients who recovered from COVID-19 (n = 39), with higher levels of IL-1β, IL-1RA, IL-7, IL-8, IL-10, IFN-γ, and MIP-1α, and a decrease in IL-9, CCL11, MIP-1β, and RANTES, as compared with healthy controls (n = 43)." (PMID 38549752, 2024). "Dynamic fluctuations in serum IL-6, IL-8, and IL-10 levels were linked to patient survival in the intensive care unit and may be used as a biomarker to predict treatment options for COVID-19 patients." (PMID 38544825, 2024). "However, cells from COVID-19 patients with the C allele significantly increase cytokine production when stimulated with spike + LPS, mainly IL-10, IL-6, and TNF-α compared to the unstimulated condition." (PMID 39456843, 2024). "Research shows that thyme and its bioactive compounds can suppress pro-inflammatory cytokines (e.g., TNF-α, and IL-6) and boost anti-inflammatory cytokines like IL-10, which may help manage inflammation linked to COVID-19." (PMID 39683135, 2024). "An increase in IL-10+ B cells was associated with positive long-term outcomes and the resolution of lung pathology in COVID-19 patients may occur by suppressing excess inflammation activity." (PMID 39063987, 2024). "Our research group has demonstrated that hDPSCs can modulated the production of cytokines such as TNFα, IFNγ, IL-10 and IL-17A by peripheral blood mononuclear cells (PBMCs) obtained from Coronavirus disease 2019 (COVID-19) patients." (PMID 39450172, 2024). "Conversely, a reduction in the frequency of IL-10+ Bregs has been associated with hyperinflammatory responses in critical and severe COVID-19 patients, supported by an increase in clinical inflammatory parameters, including neutrophil/lymphocyte ratio and the D-dimer presence." (PMID 39346706, 2024). "Indeed, we found that increased viral load is associated with more severe COVID-19 and significantly, positively correlated with IL-10, MCP-1, and MCP-3." (PMID 39633683, 2024).